AFM (afamin)
Diseases named in the same sentence as AFM in open-access papers (continued):
Sharing a sentence is not in itself a finding about the gene and the disease.
Obesity (11 papers, 2021 to 2025). Accumulation of substantial excess body fat. "Afamin is also a specific binding protein for vitamin E which has been associated with various diseases, among them obesity and T2DM." (PMID 38245742, 2024). "Our results underline the usefulness of measuring serum afamin levels in severe obesity, which demonstrate early alterations in the regulation of liver-derived hormone-like peptides." (PMID 36835525, 2023). "Former studies have reported a strong association of elevated serum afamin with various metabolic disorders, including obesity, MetS, T2DM, NAFLD, and coronary atherosclerosis." (PMID 36835525, 2023). "Elevated concentrations of afamin and their association with lipoprotein subfractions might be useful when assessing obesity-associated cardiovascular risk." (PMID 35053264, 2022). "Serum kallistatin and afamin concentrations are associated with the anthropometric parameters related to being overweight and to obesity, especially to those describing the visceral distribution of adipose tissue and metabolic disorders related to excessive fatness." (PMID 34945088, 2021). "Our results may underline the significance of serum afamin measurement in severe obesity." (PMID 36835525, 2023). "We think that there is a need for comprehensive new studies involving more patients with long-term follow-up in order to use afamin as a prognostic factor and an important marker in the follow-up and treatment of obesity in the future." (PMID 36769494, 2023). "There are studies showing that afamin can be used as a marker in ovarian malignancies whose relationship with obesity has been investigated many times." (PMID 36769494, 2023). "First, it is a cross-sectional study and thus shows no cause–effect or time–effect relationship between kallistatin and afamin levels and obesity-related anthropometric parameters." (PMID 34945088, 2021). "An extensive analysis of the literature has shown that few studies are assessing the relationship between kallistatin and afamin and obesity-related anthropometric indices in the group of patients after myocardial infarction." (PMID 34945088, 2021). "The second observation, resulting from the conducted research, concerns the relationship between the anthropometric parameters related to being overweight and obesity with the level of kallistatin and afamin." (PMID 34945088, 2021). "Although the physiologic function of afamin is largely unknown, current investigations have found that afamin is closely correlated with obesity and related metabolic diseases." (PMID 35800214, 2022). "Moreover, the concentration of kallistatin and afamin positively correlates with obesity-related anthropometric measures, especially those describing the excessive accumulation of abdominal fat (LAP) and obesity-related metabolic disorders (TyG index)." (PMID 34945088, 2021). "Serum afamin concentrations were increased in patients with prediabetes and T2D compared to lean healthy controls (p<0.001), and in patients with prediabetes compared to individuals with obesity (p<0.05)." (PMID 34603196, 2021). "BMI, fasting glucose, and intermediate and small HDL subfractions are found to be predictors of afamin in this study; therefore, afamin may serve as a potential biomarker for the severity of cardiometabolic disturbances, including impaired lipid and/or glucose metabolism in obesity." (PMID 36835525, 2023). "It has been suggested that afamin levels that are already elevated during pregnancy may cause hypertension by mechanisms independent of obesity just as beta-hCG causes in certain studies." (PMID 36769494, 2023). "The binding of afamin to small, dense HDL subfractions and the shift to these HDL fractions in obesity have been described previously." (PMID 35053264, 2022).
diabetes (10 papers, 2019 to 2025). "An increase in afamin by 10 mg/L was associated with prevalent DMT2 diabetes (OR 1.19, 95% CI 1.12, 1.26), whereas the association of afamin and vitamin E plasma level is still under debate." (PMID 33003543, 2020). "However, the causality of afamin’s association with diabetes mellitus and possible underlying mechanisms have still to be elucidated." (PMID 38245742, 2024). "Finally, higher afamin levels were associated with more pronounced increases in the HSI in the NGT subgroup than in people with prediabetes or diabetes in the prospective analyses, but these associations were only statistically significant in model 3 (pinteraction = .013)." (PMID 40631608, 2025). "Cross‐sectional associations between afamin and NAFLD LFS were also stronger in individuals with prediabetes or diabetes compared to those with normal glucose tolerance (pinteraction < .001)." (PMID 40631608, 2025). "In the cross‐sectional analyses, higher plasma afamin concentrations were associated with more pronounced increases in the NAFLD LFS in men and in people with prediabetes or diabetes (all pinteraction < .001)." (PMID 40631608, 2025). "In addition, we found a statistically significant correlation of adropin and afamin with age, weight, and height in children with up to 5 years' of lasting diabetes." (PMID 31781629, 2019). "Our data confirm the possible role of afamin in evaluating diabetes complications, being elevated in DN subjects, but reduced in both DC and NC subjects, indicating that elevated levels could predict the future progression of diabetes-related cardiovascular disease." (PMID 38245742, 2024). "The data allowed us to build models that could distinguish DKD from diabetes (AUC = 0.928) with 2 proteins (ALB, AFM), and distinguish DKD3 from DKD4 (AUC = 0.949) with 3 proteins (ANXA7, APOD, C9)." (PMID 34963468, 2021). "Afamin has also been higher in T2D patients with NAFLD than in those without NAFLD, suggesting that higher afamin concentrations are more related to liver disease than to diabetes per se." (PMID 34603196, 2021).
gestational diabetes mellitus (10 papers, 2018 to 2026). "Additionally, by proteomic analysis, afamin was determined as a predictor of gestational diabetes mellitus in pregnant women." (PMID 36361589, 2022). "In search of potential early biomarkers for timely prediction of gestational diabetes mellitus (GDM), we focused on afamin, a vitamin E–binding protein in human plasma.." (PMID 29587878, 2018). "In a nested case-control proteomic analysis study, sera from 60 obese women with gestational diabetes mellitus (GDM) identified three candidate predictors of GDM: SAP, afamin, and vitronectin." (PMID 32967132, 2020).
ovarian carcinoma (9 papers, 2012 to 2022). A malignant neoplasm originating from the surface ovarian epithelium. "al. also measured decreased plasma concentrations of Afamin and APOA4 in patients with ovarian cancer, with APOA4 adding independent diagnostic information to CA125 and age for differentiating ovarian cancer from benign and healthy samples." (PMID 25265318, 2014). "Comparative proteomics has previously identified afamin as a potential biomarker for ovarian cancer." (PMID 23981841, 2013). "Patients with ovarian cancer displayed significantly decreased plasma concentrations of afamin by comparison to healthy controls." (PMID 23981841, 2013). "Comparative proteomics has recently identified afamin, the newest member of the albumin gene family, as a potential biomarker for ovarian cancer." (PMID 23981841, 2013). "Previously, proteomic studies identified afamin as a potential biomarker of ovarian cancer." (PMID 36361589, 2022). "Also, afamin has been known to be a tumor marker for some cancer types including ovarian cancer where afamin is likely involved in regulation of the bone metabolism and signaling pathways (Dieplinger & Dieplinger, 2015 ▶)." (PMID 33907673, 2021). "A low afamin level in serum has been reported in ovarian cancer and CCA." (PMID 32845921, 2020). "AFM, a member of the albumin family, is a vitamin E-binding protein that was reported as a novel protein marker for ovarian cancer and may be a negative acute-phase protein, although the pathophysiology is unclear at present." (PMID 25435926, 2015). "Furthermore, several other proteomic studies have identified afamin as a potential biomarker in other disorders, including simian immunodeficiency virus (SIV) induced central nervous system disease, ovarian cancer, congenital disorders of glycosylation and Down syndrome." (PMID 24433274, 2014).
polycystic ovary syndrome (7 papers, 2014 to 2024). A disorder that manifests as multiple cysts on the ovaries. "Higher levels of oxidative stress lead to increased levels of afamin; higher concentrations of this protein are found in endometriosis, metabolic syndrome, insulin resistance, PCOS (polycystic ovary syndrome) and T2DM." (PMID 38892323, 2024).
Hypertension (6 papers, 2018 to 2024). The presence of chronic increased pressure in the systemic arterial system. "Oxidative stress is involved in the pathogenesis of hypertensive disorders such as preeclampsia (PE) and associated with the human vitamin E-binding protein afamin." (PMID 30220025, 2018).
breast carcinoma (3 papers, 2011 to 2019). "With 2D-nanoLC-MS/MS, afamin, apolipoprotein E and isoform 1 of inter-alpha trypsin inhibitor heavy chain H4 (ITIH4) were found to be higher in pre-diagnostic breast cancer (p < 0.05), while alpha-2-macroglobulin and ceruloplasmin were lower (p < 0.05)." (PMID 21871081, 2011). "Of the proteins detected with 2D-nanoLC-MS/MS, afamin, apolipoprotein E and an isoform of ITIH4 were slightly, but significantly higher and alpha-2-macroglobulin and ceruloplasmin slightly, but significantly lower in pre-diagnostic breast cancer samples compared to control samples." (PMID 21871081, 2011).
endometriosis (3 papers, 2014 to 2023). The growth of functional endometrial tissue in anatomic sites outside the uterine body. "Another study showed that afamin was also significantly higher in the peritoneal fluid of patients with endometriosis." (PMID 36769494, 2023). "Higher level of the binding protein Afamin suggests reduced amounts of available antioxidant to scavenge the free radicals and thereby provides a linkage between endometriosis and oxidative stress." (PMID 24900998, 2014). "Several experiments have shown an increase in levels of Afamin in peritoneal fluid of patients with endometriosis when compared to women who are disease free." (PMID 24900998, 2014).
Hepatic steatosis (3 papers, 2023 to 2025). Steatosis is a term used to denote lipid accumulation within hepatocytes. "The present study aimed to investigate the associations between afamin and fatty liver and fibrosis indices and to study potential modifying effects of sex and glucose tolerance status on these associations in individuals from the population‐based KORA F4/FF4 cohort." (PMID 40631608, 2025). "Among 469 detected EV proteins, 60 differed by hepatic steatosis status (p < 0.05), with two proteins remaining significant after multiple testing correction: complement C4A (C4A) and afamin (AFM)." (PMID 41354933, 2025). "After correcting for multiple comparisons, two proteins remained significant (q < 0.05): C4A (complement factor 4A), which was decreased in hepatic steatosis, and afamin (AFM), which was increased." (PMID 41354933, 2025). "Prospective associations of afamin levels at KORA F4 with the NAFLD liver fat score, hepatic steatosis index and fibrosis‐4 index at KORA FF4." (PMID 40631608, 2025). "Cross‐sectional associations between afamin and the NAFLD liver fat score, hepatic steatosis index and fibrosis‐4 index at the baseline examination KORA F4." (PMID 40631608, 2025). "In participants with severe hepatic steatosis (n = 43), subgroup analysis showed increased COL18A1, AFM, PRG4, and INHBE and decreased C4A and APOA1." (PMID 41354933, 2025). "In the cross‐sectional analysis, afamin concentrations were positively associated with NAFLD LFS (β = .32; 95% CI .27–.37), hepatic steatosis index (β = .33; 95% CI .26–.39) and fatty liver index (β = 1.78; 95% CI 1.47–2.08) (all p < .001), but not with fibrosis‐4 index." (PMID 40631608, 2025).
Nephropathy (3 papers, 2021 to 2025). A nonspecific term referring to disease or damage of the kidneys. "Lastly, the urinary afamin to creatinine ratio has been proposed as a useful marker to predict patients with T2DM at high risk of nephropathy before the development of macroalbuminuria or reduced kidney function." (PMID 38245742, 2024). "Our results align with the growing body of evidence that underscores Afamin as a promising biomarker for renal disease." (PMID 41394867, 2025).
prediabetes (3 papers, 2021 to 2025). "We observed a slight but significant decrease of afamin concentrations within the first 60min of the oGTT in patients with prediabetes and T2D." (PMID 34603196, 2021). "Moreover, our study found that cross‐sectional analyses between afamin and NAFLD LFS were higher in individuals with prediabetes or T2D compared to those with NGT." (PMID 40631608, 2025). "When adjusted for age, afamin remained significantly different between lean healthy controls and patients with prediabetes (p<0.001) and T2D (p< 0.05), however not between obese and prediabetic patients." (PMID 34603196, 2021). "We observed that apart from the slight but significant decrease within the first 60 min of oral glucose tolerance test, which was specific for patients with prediabetes and T2D, afamin is not markedly regulated by acute oral glucose load." (PMID 34603196, 2021).
steatosis (3 papers, 2024 to 2025). Increased lipid within the cytoplasm of cells. "Afamin (AFM), angiotensinogen (AGT), β-defensin 1 (DEFB1), and PRAP1 were correlated with steatosis; DEFB1 was correlated with the NAS; and 90 proteins were associated with hepatocyte ballooning." (PMID 40250425, 2025). "In a protein–protein interaction network, IGSF9 was found to have a central position, being correlated to FGF21, CES1, MAMDC4, and afamin (AFM) in PLHIV with steatosis, and to AFM and GHR in those without steatosis." (PMID 39426127, 2024).
COVID-19 (2 papers, 2023). A disease caused by infection with severe acute respiratory syndrome coronavirus 2. "We also found that five proteins (Afamin, I-309, NKG2A, PRS57, LIPK) and patient age serve as a signature that separates patients with mild COVID-19 and patients with moderate/severe COVID-19 with an error rate of 1.77% (AUC = 0.9804)." (PMID 37985892, 2023).
diabetic kidney disease (2 papers, 2023 to 2024). Progressive kidney disorder caused by vascular damage to the glomerular capillaries, in patients with diabetes mellitus. "Studies have shown that alpha-1-antitrypsin and afamin are potential biomarkers for the diagnosis of early diabetic kidney disease (DKD) and can predict the decline in renal function." (PMID 38402394, 2024). "Furthermore, measurement of urinary afamin and RBP4 may serve as biomarkers for the accurate diagnosis of diabetic nephropathy and might help to reduce the burden associated with renal biopsy in patients with diabetic nephropathy." (PMID 36835525, 2023).
Hepatic fibrosis (2 papers, 2025). The presence of excessive fibrous connective tissue in the liver. "Future studies need to elucidate whether afamin also contributes to the pathogenesis of MASLD and whether afamin plays a role in hepatic fibrosis." (PMID 40631608, 2025). "The APASHA model—consisting of APOF, PCSK9, AFM, S100A6, HbA1c %, and AZGP1—showed an excellent discriminatory capacity with an AUROC of 0.8875 (CI 0.82–0.96) to discriminate MASH, but not liver fibrosis." (PMID 40250425, 2025). "Therefore, the knowledge on afamin's role in MASLD and liver fibrosis is currently not well understood." (PMID 40631608, 2025).
hyperlipidemia (2 papers, 2022 to 2023). "Elevated levels of afamin in mice are positively correlated with the increase in body weight, cholesterol, triglycerides, and glucose levels that induce the state of hyperlipidemia." (PMID 37835901, 2023). "Elevated levels of afamin in mice are positively correlated with the increase in body weight, total cholesterol, TG, and glucose levels that induce the state of hyperlipidemia." (PMID 37835901, 2023). "While the physiological functions of afamin are not well understood, its overexpression in transgenic mice lead to increased body weight as well as hyperglycemia and hyperlipidemia." (PMID 36104811, 2022).
IgA nephropathy (2 papers, 2013 to 2026). "Transcriptomic-wide MR identified candidate genes across GN subtypes: RECQL, BRSK2, and MGP in acute GN; AFM, CFHR5, and EPHB2 in chronic GN; IL6R, MBL2, and PRSS3 in IgA nephropathy; and TIMP4, HCK, and PEAR1 in membranous nephropathy." (PMID 41990104, 2026).
liver cancer (2 papers, 2017 to 2022). An epithelial or non-epithelial malignant neoplasm that arises from the liver. "Upregulation of POSTN, LAYN and HTRA3 and downregulation of AANAT and AFM were positively related to poorer overall survival in human liver cancer." (PMID 35676936, 2022). "Overall, the survival analysis based on the DEGs suggests that the expression of POSTN, HTRA3, LAYN, AFM and AANAT are associated with the outcomes of patients with liver cancer." (PMID 35676936, 2022).
liver disease (2 papers, 2019 to 2021). "Plasma proteome profiling of 48 patients with and without cirrhosis or NAFLD revealed six statistically significantly changing proteins (ALDOB, APOM, LGALS3BP, PIGR, VTN, and AFM), two of which are already linked to liver disease." (PMID 30824564, 2019).
membranous nephropathy (2 papers, 2023 to 2026). "A study conducted with a similar but larger population indicated a significant increase in urinary afamin in primary membranous nephropathy." (PMID 36769494, 2023).
non-alcoholic fatty liver disease (2 papers, 2020 to 2024). "Even though the physiological properties of this hepatokine are not fully characterized, increasing evidence has shown that afamin is strongly associated with MS, T2DM, non-alcoholic fatty liver disease (NAFLD) and other IR-related conditions." (PMID 38379862, 2024).
prostate carcinoma (2 papers, 2012 to 2022). A carcinoma that arises from epithelial cells of the prostate gland. "Thus, the potential of afamin as a candidate prostate cancer biomarker requires further study." (PMID 22355332, 2012).
Type 1 Diabetes (2 papers, 2019 to 2023). "Assessment of serum levels of adropin, afamin, and neudesin in children with type 1 diabetes, with respect to the disease duration." (PMID 31781629, 2019). "The results of our analysis showed that the mean levels of adropin and afamin were statistically lower in children with type 1 diabetes as compared to the control group, whereas mean neudesin concentration was statistically higher in diabetic patients." (PMID 31781629, 2019). "Patients with normal endocrine function of the pancreas have, respectively, higher levels of adropin and afamin and lower level of neudesin as compared to individuals suffering from type 1 diabetes." (PMID 31781629, 2019). "Also, in the context of oxidative stress, the vitamin E binding protein AFM was less abundant in the individuals with type 1 diabetes than in the UFMs." (PMID 37537394, 2023).
bladder cancer (1 paper, 2022). "We previously discovered potential urine protein biomarkers indicating the occurrence of bladder cancer, including afamin, adiponectin, complement C4 gamma chain, apolipoprotein A-II precursor, ceruloplasmin, and prothrombin using multiplex reaction monitoring mass spectrometry (MRM-MS)." (PMID 36428492, 2022).
dengue (1 paper, 2012). "However, in order to increase the probability to find potential biomarkers for severe dengue, we choose to include three additional proteins (Vitamin D Binding-Protein, Afamin and Fibronectin)." (PMID 23101585, 2012).
fibrosis (1 paper, 2025). the formation of excess fibrous connective tissue in an organ or tissue in a reparative or reactive process. "Moreover, the cross‐sectional associations between afamin concentrations and the FIB‐4 index as a fibrosis marker were assessed." (PMID 40631608, 2025).